RNU6-1132P (RNA, U6 small nuclear 1132, pseudogene)
Gene: Small nuclear RNA gene on chromosome 2 (132,152,243 to 132,152,349, reverse strand). Ensembl gene ENSG00000239108.
Homologues: Orthologues: chimpanzee U6 (100% identical), macaque U6 (90% identical), rabbit U6 (64% identical), dog U6 (64% identical), rabbit U6 (61% identical), pig U6 (60% identical). Paralogues in human: RNU6-614P (98% identical), U6 (97% identical), RNU6-1293P (96% identical), RNU6-156P (96% identical), RNU6-721P (96% identical), RNU6-458P (95% identical), U6 (95% identical), RNU6-1207P (91% identical), RNU6-811P (91% identical), RNU6-978P (91% identical), RNU6-452P (86% identical), RNU6-666P (85% identical), and 1289 more.